MALT1 (MALT1 paracaspase)
Diseases named in the same sentence as MALT1 in open-access papers (continued):
Sharing a sentence is not in itself a finding about the gene and the disease.
pulmonary lymphoma (1 paper, 2021). "This is the first study to analyze the diagnostic utility of IGH and TCR rearrangements in clonality analyses in addition to MALT1 translocation in BALF of patients with clinically suspected pulmonary lymphoma." (PMID 34873224, 2021). "In this study, we analyzed the feasibility of using BALF for combined detection of lymphocyte clonality based on IGH and TCR rearrangements as well as MALT1 translocations to diagnose pulmonary lymphomas." (PMID 34873224, 2021). "In conclusion, we evaluated the utility of the combined detection of clonality and MALT1 translocations in BALF for the diagnosis of pulmonary lymphomas." (PMID 34873224, 2021). "Detection of additional genetic aberrations such as MALT1 translocations in BALF cells can further specify the type of pulmonary lymphoma." (PMID 34873224, 2021). "We analyzed B- and T-cell clonality based on IGH and T-cell receptor (TCR) rearrangements together with MALT1 translocations using BALF of patients with clinically suspected pulmonary lymphomas." (PMID 34873224, 2021).
reactive arthritis (1 paper, 2022). Reactive arthritis (ReA) is an autoimmune disorder belonging to the group of seronegative spondyloarthropathies and is characterized by the classic triad of arthritis, urethritis and conjunctivitis. "Besides, MALT1 was also higher in RA patients compared to reactive arthritis patients (P<0.001), which also related to RA risk vs. reactive arthritis with AUC: 0.752." (PMID 35967391, 2022).
systemic lupus erythematosus (1 paper, 2020). An autoimmune multi-organ disease typically associated with vasculopathy and autoantibody production. "Our studies indicate that a MALT1 allosteric inhibitor affecting both scaffold and protease activity can be considered as a potential treatment for autoantigen-driven autoimmune pathology due to its effect on TCR- and BCRmediated activation, such as type 1 diabetes and systemic lupus erythematosus." (PMID 32870913, 2020).
thymoma (1 paper, 2021). A neoplasm arising from the epithelial cells of the thymus. "The results showed that there was a significant negative correlation between MALT1 expression and TMB in PRAD, THCA, BRCA, CHOL, and ESCA (cor <0, p < 0.05) but a significant positive correlation between MALT1 expression and TMB in COAD, LGG, and thymoma (THYM) (cor >0, p < 0.05)." (PMID 34926571, 2021).
triple-negative breast carcinoma (1 paper, 2023). An invasive breast carcinoma which is negative for expression of estrogen receptor (ER), progesterone receptor (PR), and human epidermal growth factor receptor 2 (HER2). "Notably, MALT1 drives epithelial-to-mesenchymal transition (EMT) in claudin-low, triple-negative breast cancer (TNBC) with overexpression of selected G protein-coupled receptors (GPCRs), suggesting MALT1 as a novel oncogenic signaling molecule in a subset of GPCR+TNBCs." (PMID 36797769, 2023).
vitiligo (1 paper, 2020). Generalized well circumscribed patches of leukoderma that are generally distributed over symmetric body locations and is due to autoimmune destruction of melanocytes. "MS and vitiligo shared 37 differentially expressed (positive co-expressed) genes, all of which showed contradictory expressions exceptSPEN,NEAT1,MIR612,MALT1 andKMT2A (similar expression)." (PMID 33763205, 2020).
tumor (70 papers, 2013 to 2026). "Zhou and collaborators have reported a novel mechanism that targeting tumor exosomal circular RNA cSERPINE2 suppresses breast cancer progression by mediating MALT1-NF-κB-IL-6 axis of tumor-associated macrophages." (PMID 38926780, 2024). "As the survival analysis showed that MALT1 expression level was positively associated with the improved prognosis of patients after immunotherapy, we treated tumor-bearing WT or Malt1−/− mice with anti-PD-1 to compare with IgG control." (PMID 33963274, 2021). "GSEA showed that MALT1 was associated with several tumor-related pathways, including the androgen response, G2M checkpoint, NF-κB signaling pathway, Wnt/β-catenin pathway and TGF-β signaling pathway." (PMID 34926571, 2021). "This phenomenon clearly indicated that knocking out MALT1 disrupts tumour cell proliferation and causes cell apoptosis in vivo." (PMID 32452133, 2020). "Since the tumor microenvironment was composed of a large number of immune cells, we then examined the association between MALT1 copy number and infiltration level of several immune cells in PCa, such as B cell, CD4+ T cell, CD8+ T cell, macrophage, neutrophil and dendritic cell (DC)." (PMID 34926571, 2021). "These MALT1 protease inhibitors have been shown to effectively suppress tumor growth in xenograft models of ABC-DLBCL." (PMID 40231473, 2025). "MALT1 protected CD274 mRNA from degradation and promoted the proliferation and polarization of tumor-associated macrophages to create an immunosuppressive tumor microenvironment." (PMID 40725006, 2025). "MALT1 also influences the tumor microenvironment by maintaining immune-suppressive regulatory T-cells." (PMID 40338274, 2025). "In GBM, MALT1 inhibition, such as with MI-2, leads to reduced tumor cell proliferation, migration, and invasion, induces G1 cell cycle arrest, and enhances immune reactivity in the tumor microenvironment, making it a promising therapeutic target." (PMID 40338274, 2025). "Inhibition of MALT1 in tumor-bearing mice with a drug induces Treg cells to secrete the immunostimulatory cytokine IFNγ only in tumor tissue, resulting in stunted tumor growth." (PMID 37828948, 2023). "Due to its association to different signaling pathways, as the EGFR induced NF-κB activation, MALT1 has been described as an essential protein for tumor progression in preclinical models." (PMID 36745330, 2023). "In JeKo-1 cells with MALT1 KO, we observed a significant decrease in the frequency of tumor cells in the spleen (P < 0.0001), liver (P < 0.0001), BM (P < 0.0001), and PB (P < 0.01)." (PMID 36719376, 2023). "To assess the long-term effect of MALT1 inhibition on MCL tumor dissemination, we established PDX models by intravenous injection of IBN-R PDX cells." (PMID 36719376, 2023). "BTK KD in the JeKo-1 cells showed comparably decreased tumor cell presence in the spleen (P < 0.001) and BM (P < 0.001), which was also seen with MALT1-KO cells." (PMID 36719376, 2023). "Whereas most studies describe a tumor-promoting role for MALT1, a recent study suggests that MALT1 can also act as a tumor suppressor." (PMID 35203553, 2022). "Our xenograft animal study illustrates that CAPE treatment effectively attenuated tumor growth in vivo by downregulating MALT1 and upregulating NDRG1 expression in PC-3 cells." (PMID 35053438, 2022). "Silencing or pharmacological inhibition of MALT1 reduces the proliferative and invasive potential of the tumor cells both in vitro and in vivo." (PMID 35203553, 2022). "Although the expression and activity of MALT1 and NF-κB are tightly controlled, some tumor cells can override these negative regulatory mechanisms to favor tumor progression." (PMID 35203553, 2022).
tumor (continued). "Highly mutated genes like BARD1, MALT1, BRCA1/BRCA2, EIF3K, PTEN, FGFR2, and MAP3K1 were also found to overlap with SVs of the tumor sample that were identified by one or more technologies in our study." (PMID 36514120, 2022). "Excitingly, incomplete inhibition of the C11BM complex either by reducing CARD11 expression or by pharmacological inhibition of MALT1 prevents lethal autoimmune reactions, but converts tumor-infiltrating Treg cells into IFNγ-secreting effector T cells." (PMID 35203553, 2022). "Constitutive MALT1 activity has been found to drive proliferation, survival, and metastasis in several tumor entities, such as lymphoid malignancies and solid tumors, and it is considered a crucial player in persistent NF-κB activation." (PMID 35203553, 2022). "Both pancreatic ductal adenocarcinoma (PDAC) and prostate cancer (PCa) cells show increased MALT1 expression that contributes to tumor malignancy and metastasis." (PMID 35203553, 2022). "In vivo experiments also demonstrated that MALT1 knockdown or its protease activity inhibition led to a decrease of phosphorylated p65 in mice subcutaneous tumor tissues." (PMID 35309901, 2022). "MALT1 knockdown reduces proliferation, invasion, and migration in PCa cell lines, as well as attenuates xenograft tumour establishment in nude mice." (PMID 36009554, 2022). "The transcription factor Elk-1 directly binds to the MALT1 promoter, thus contributing to MALT1 overexpression in the tumor cells." (PMID 35203553, 2022). "The high-grade MES GBM can downregulate miR-181d, thus increasing MALT1-dependent NF-κB activation and enhancing tumor burden and aggressiveness." (PMID 35203553, 2022). "In CBM-dependent tumor cells, MALT1 inhibition directly acts on their proliferative and invasive potential, while, at the same time, it destabilizes the Treg-mediated immunosuppression." (PMID 35203553, 2022). "Deregulated MALT1 activity in cancer thus promotes tumor cell survival, proliferation, and metastasis." (PMID 35203553, 2022). "It was observed by microscope that MALT1 was mainly expressed in tumor tissues, and the IHC scores of tumor tissues were significantly higher than those in adjacent tissues (p < 0.001)." (PMID 35309901, 2022). "In vivo, suppressing the MALT1 expression or its proteasome activity effectively reduced the size of the subcutaneous tumor in nude mice." (PMID 35309901, 2022). "All these results demonstrated that after downregulating the expression of MALT1, the invasion and migration ability of tumor cells decreased, and the difference was statistically significant." (PMID 34926571, 2021). "In the terms of MALAT1 expression in tumor patients, most of the published papers showed the overexpression of MALT1 in tumor samples." (PMID 34308750, 2021). "Authors have identified very significant correlation of MALT1 expression with tumor burden and various cancer driven pathways in multiple cancers." (PMID 34926571, 2021). "The correlation between MALT1 expression and tumor-infiltrating immune cells was analyzed by the TIMER database." (PMID 34926571, 2021). "The knockdown of MALT1 in highly metastatic PC-3 cells decreased cell growth in vitro and tumor growth in vivo." (PMID 33802402, 2021). "H&E staining showed that tumours derived from MALT1‐knockout U87 cells were significantly smaller than those of the control group." (PMID 32452133, 2020). "Compared with the control, a lower number of Ki67‐positive tumour cells were observed in the MALT1‐knockout mice." (PMID 32452133, 2020). "Administration of the Malt1 inhibitors mepazine or MI-2 significantly delays tumor growth when injected in a curative schedule, alone or in combination with a tumor vaccine." (PMID 33143070, 2020). "Immunostained tumour tissues isolated from control and MALT1‐knockout mice were used to evaluate the effect of MALT1 knockout on cell proliferation and apoptosis in vivo." (PMID 32452133, 2020).
tumor (continued). "After standardization by each corresponding normal tissues, the MALT1 expression in patients' tumor tissues displayed higher expressions (Ranging from 5.87 to 201.6 folds)." (PMID 31788131, 2019). "Several small molecule MALT1 inhibitors, which inhibit the protease activity of MALT1, have shown remarkable anti-tumor effects on ABC DLBCL cells in vitro and in vivo." (PMID 30881917, 2019). "Ectopic expression of miR181d and the consequent downregulation of MALT1 suppresses growth of tumor cells." (PMID 30214442, 2018). "MALT1 protease activity plays an essential role in activation of NF-κB, which functions as a transcription factor of PD-L1 in tumor cells." (PMID 30619766, 2018). "Subcutaneous tumor growth analysis revealed that MALT1 gene silencing significantly reduced tumor growth and metastasis to the lung." (PMID 28759024, 2017). "Cells expressing MALT1 shRNA displayed a significantly reduced tumor growth kinetic as compared with the control cells and consequently produced tumor nodules with significantly lower weight than control tumors." (PMID 28759024, 2017). "Moreover, their research revealed that API2-MALT1 paracaspase-mediated function leads to the cleavage of EPLIN-α, resulting in the loss of its tumor suppressor activity both in vitro and in vivo." (PMID 38732188, 2024). "We next examined whether si-cSERPINE2-NPs treatment of tumor cells could influence the cSERPINE2 and MALT1 levels in TAMs." (PMID 36797769, 2023). "Recent studies have indicated that MALT1 inhibition impairs immune suppressive function of regulatory T cell in the TME, indicating that MALT1 may suppress anti-tumor immunity in solid cancers." (PMID 36797769, 2023). "Additionally, BTK knockdown and MALT1 knockout markedly impaired MCL tumor migration and dissemination, and MALT1 pharmacological inhibition decreased MCL cell viability, adhesion, and migration by suppressing NF-κB, PI3K/AKT/mTOR, and integrin signaling." (PMID 36719376, 2023). "Potentially, MALT1 inhibition could be used to simultaneously target both tumor cells and suppressive immune cells." (PMID 35203553, 2022). "Furthermore, knockdown of the MALT1 interaction partner TRAF6 abolishes NF-κB activation, pinpointing the importance of MALT1 as a scaffold protein to bridge TRAF6 to the IKK complex in response to EGF in this tumor entity." (PMID 35203553, 2022). "Taken together, these results showed that the inhibition of MALT1 or its protease activity could suppress tumor growth and migration in vivo." (PMID 35309901, 2022). "Nevertheless, it is tempting to speculate that a short-term application of MALT1 inhibitors in combination with immune checkpoint inhibitors could support the T cell-mediated anti-tumor reaction and thus prove beneficial for cancer patients." (PMID 35203553, 2022). "To evaluate the pro-oncogenic function of MALT1 in vivo, we established a subcutaneous tumor model." (PMID 35309901, 2022). "Indeed, the use of either allosteric or active site MALT1 inhibitors has revealed significant anti-tumor effects in the treatment of solid tumors both in vitro and in vivo." (PMID 35203553, 2022). "Moreover, the correlation between MALT1 expression and tumor immune infiltration was analyzed by the Tumor Immune Evaluation Resource (TIMER) database." (PMID 34926571, 2021). "MALT1 promoted proliferation and colony genesis while reducing PCa cell apoptosis levels, and MALT1 suppression could inhibit xenograft tumor establishment in nude mice." (PMID 34926571, 2021). "Therefore, our study provides novel evidence that lncRNA HOXD-AS2 is indispensable for GBM tumor growth by regulating miR-3681-5p/MALT1 axis." (PMID 34802389, 2021).
tumor (continued). "Additionally, the correlations between MALT1 expression and mismatch repair (MMR) gene mutation, immune checkpoint gene expression, tumor mutational burden (TMB), and microsatellite instability (MSI) were investigated by Pearson correlation analysis." (PMID 34926571, 2021). "MALT1 promoted cell proliferation, invasion, and tumor growth in vitro and in vivo." (PMID 33802402, 2021). "MALT1 has been proven to be overexpressed in various solid tumors, and increasing numbers of research studies have confirmed that MALT1 is a key regulator of tumor development." (PMID 34926571, 2021). "Therefore, MI‐2 can be used as a therapeutic agent for the treatment of tumours that are dependent on MALT1 signals." (PMID 32452133, 2020). "Mepazine was successfully tested as a therapy in Malt1-dependent tumor models as well as in EAE." (PMID 33042160, 2020). "However, infection only serves as a trigger, and the leading cause of the pathology seems to be the self-proliferation of tumor cells due to MALT1 translocation under transcriptional control in the IgH enhancer region, activated by infection." (PMID 33121169, 2020). "Recent studies have shown that MALT1 as an oncogene is up‐regulated in various solid tumours and may be a key factor for tumour development." (PMID 32452133, 2020). "This raises the interesting possibility that, at least in the context of cancer, MALT1 inhibitors may exert their effects by a dual action on both the inhibition of the growth of cancer cells and boosting anti-tumor immune responses." (PMID 30214442, 2018). "In BJAB B cells stable BCL10-CARD11 expression activates MALT1 and NF-κB as strong as oncogenic variants of CARD11 derived from DLBCL tumor patients, clearly showing that the proximity of BCL10 and CARD11 alone is sufficient to activate downstream signaling pathways." (PMID 30515170, 2018). "Since tumor tissues from both patients were MALT1-positive, this implies that MALT1 may have the potential to be a predictive biomarker for response to regorafenib." (PMID 29371921, 2017). "However, MALT1-targeted therapy poses a dual challenge: although inhibiting oncogenic signaling and tumor cell proliferation, it also disrupts immunosuppressive Treg function, risking autoimmune toxicity by compromising the tumor microenvironment." (PMID 41783325, 2026). "We found that tumor development was enhanced in mice with a specific deletion of Malt1 in T cells, but not in macrophages, similar to the phenotype observed in Malt1 germline knockout (KO) mice, implying that Malt1 in T cells is critical in antitumor immune response." (PMID 33963274, 2021). "Moreover, in tumor bearing Malt1-deficient mice, mepazine did not affect the growth of the MALT1-competent tumor cells themselves." (PMID 31138793, 2019). "Interestingly, the tumor tissues of both cases were MALT1-positive." (PMID 29371921, 2017). "Therefore, it is likely that, in addition to promoting cell survival through NF-κB signaling, MALT1 overexpression may enhance the capacity and scope of cell adhesion to prevent BTKi-induced lymphocytosis and tumor cell killing and thus confer BTKi resistance and immune evasion." (PMID 36719376, 2023). "Analysis of tumor-infiltrating lymphocytes showed decreased CD8+ T-cell infiltration and IFN-γ or Granzyme B production in Malt1−/− mice." (PMID 33963274, 2021). "CARD9 was equally immunoprecipitated from total cell protein lysates of each group, but Bcl10 and MALT1 attached to CARD9 increased nearly 2 and 3 folds respectively on NLGP addition to the tumor-conditioned cells, suggesting the trimolecular complex formation because of the NLGP-transduced signal." (PMID 38649988, 2024).